CXCL8 (C-X-C motif chemokine ligand 8)
Diseases named in the same sentence as CXCL8 in open-access papers (continued):
Sharing a sentence is not in itself a finding about the gene and the disease.
tumor (continued). "Some researchers found, that CXCL8 is a potential biomarker of tumor burden and aggressiveness, not only in HCC, but also other types of tumors (i.e., melanoma, renal cell carcinoma and non-small-cell lung cancer." (PMID 36012108, 2022). "Consistent with previous studies, DDR can lead to the production of cancer-related inflammation, which induces TME-secreting factors such as TNF, IL-1, CCL2, and CXCL8; and activates transcription factors of NF-Κb, Stat-3, thus promoting tumor proliferation." (PMID 35413945, 2022). "Another striking difference between the Dx and Re is that genes associated with the tumor microenvironment, the interaction between stroma cells and leukemic blasts (CXCR4 and CXCL8) were lower expressed in cluster 5 (Re) compared to cluster 4 (Dx)." (PMID 35986270, 2022). "They found that in a considerable number of DLBCL patients, tumor cells constitutively produce the chemokine CXCL8, enabling them to recruit APRIL to induce neutrophils." (PMID 35181719, 2022). "CXCL8 also recruits chemotactic neutrophils to tumor sites and stimulates them to produce a variety of chemo-attractant molecules." (PMID 35269652, 2022). "Tumor cells with senescent characteristics induce targeted migration of CD56dim NK cells by secreting CXCL8, which in turn initiates an innate anti-tumor immune response." (PMID 36532071, 2022). "In the studies on chemokine-mediated macrophages, cellular CXCL8 was the first chemokines found to be associated with TC, and cell lines from PTC and ATC were found to contain high levels of CXCL8 and TAMs, leading to tumor proliferation and metastasis." (PMID 35479325, 2022). "Recent studies have shown that CXCL8 is essential for tumor cells to acquire and maintain this aggressive phenotype." (PMID 36233212, 2022). "The activation of Stat3 induced the secretion of glutamic acid-leucine-arginine (ELR) motif CXCLs (CXCL1, CXCL2, CXCL3 and CXCL8) in tumor cells." (PMID 35280694, 2022). "CXCL8 has been found to affect angiogenesis, tumor genetic diversity, immune escape, proliferation and metastasis, and multidrug resistance." (PMID 36118853, 2022). "Human CXCL8 (IL-8) is produced by stromal and tumor cells and is one of the best studied neutrophil chemo-attractants in cancer." (PMID 35328639, 2022). "In the present study, we found that high levels of CXCL8 in GC tumors correlated with advanced tumor progression and poor patient survival." (PMID 35321317, 2022). "The overexpression of FOXS1 promotes tumor angiogenesis, invasion, and metastasis by upregulating C–X–C motif chemokine ligand 8 (CXCL8)." (PMID 35898871, 2022). "DARC can internalize chemokines (i.e., CCL2, CCL11, CXCL1, CXCL2, CXCL3, CXCL5, CXCL7, CXCL8) that promote angiogenesis or formation of blood vascular, which can foster tumor growth, as well as promote endothelial cell survival via inhibiting apoptosis." (PMID 36497078, 2022). "When stromal CXCL8 scores were combined with tumour‐infiltrating macrophage counts or systemic neutrophil counts, patients classified as high for both markers had significantly poorer prognosis." (PMID 35879507, 2022). "Analysis of differentially expressed genes revealed several differentially expressed genes in the HK-II high expressors associated with tumor progression (for example, VEGFA, CXCL8, and S100A being up-regulated)." (PMID 35677429, 2022). "High CXCL8 within the stromal compartment was significantly associated with a higher TSP (p = 0.040) and higher frequency of tumour budding (p = 0.002)." (PMID 35879507, 2022). "The Chemokine CXCL8 is well accepted to play a crucial role in tumor survival, invasion, and TME angiogenesis, immune suppression via several types of intracellular signaling pathway." (PMID 35372515, 2022). "For tumour cell CXCL8 expression, 95 patients were classified as high and 290 fell into the low group." (PMID 35879507, 2022).
tumor (continued). "The number of CXCL8-positive tumor cells in ESCC tumor tissues is significantly increased compared with matched adjacent tissues." (PMID 36295640, 2022). "The activation of hypoxia signaling increases the expression of adipokines, especially the pro-inflammation adipokines (including CCL2, CXCL8, CXCL10, IL-18, IL-1α and Oncostatin M), which is involved in the recruitment of tumor-associated immune cells." (PMID 35350384, 2022). "When the CXCL8-CXCR1/2 pathway was blocked by CXCL8-neutralizing antibodies in a mouse model study, tumor growth, angiogenesis, and metastasis were significantly inhibited." (PMID 36612163, 2022). "CRC cells can express and secrete CXCL8 by autocrine, which can promote angiogenesis and neutrophil infiltration in tumor tissues, so as to enhance tumor proliferation and survival." (PMID 35845924, 2022). "Latest evidence suggested that CXCL8 has the ability to recruit immunosuppressive cells and inhibit anti-tumor immune response." (PMID 36358719, 2022). "Present studies have proved that CXCL8 is essential for tumor cells to acquire and maintain this aggressive phenotype." (PMID 35372515, 2022). "Particularly, in addition to the tumor immune escape pathway, genetic markers belonging to the cytokines/interleukins, including CXCL8, CCL5, CCR5 and angiogenic mediators including IGF1, IRF3, NOS2, appear to be the most promising." (PMID 36432658, 2022). "Evidence suggests that tumor cells promote the release of NETs from neutrophils through stimulation, such as secretion of IL-8/CXCL8 and CXCR1/CXCR2 agonists, which provides an explanation for the link between NETs and cancer." (PMID 36341351, 2022). "In parallel, treatment of the tumor cells by i-Ras also led to a reduction of their extracellular levels: 35–40%, 90–95% and 75–85% inhibition of CXCL8, CCL2 and CCL5, respectively." (PMID 35205789, 2022). "CXCL8 expression was high in six tumor types with a high frequency of cachexia (STAD, ESCA, COAD, PAAD, READ, and HNSC)." (PMID 35159388, 2022). "CXCL8 can promote tumor proliferation, survival, invasion, angiogenesis, tumor stemness and suppress anti-tumor immunity in direct and indirect manner." (PMID 35372515, 2022). "The expression of serum anti-CXCL8 autoantibody in clinical subgroups divided by gender, age, tumor site, family tumor history, differentiation, TNM stage, lymphatic metastasis, and distance metastasis was further studied." (PMID 36295640, 2022). "IL-8 is also known to promote tumor migration, invasion, angiogenesis, and metastasis (CXCL8 C-X-C motif chemokine ligand 8 [Homo sapiens (human)]—Gene—NCBI (nih.gov)." (PMID 36035163, 2022). "In ovarian tumor, CXCL8 promotes the recruitment of tumor associated neutrophils in TME and activates JAG2 in tumor-associated neutrophils, which, in turn, suppresses the activity of the CD8+ T cells." (PMID 36091114, 2022). "In Oncomine database and UAICAN database, we analyzed the expression of CXCL8/9/10/11/13 in HNC tumors to find the difference in the expression level of CXCL8/9/10/11/13 in tumor and normal samples." (PMID 35905218, 2022). "Preclinical studies also suggest that combined CXCL8 blockade and ICIs therapy can enhance the anti-tumor efficacy, and several clinical trials are being conducted to evaluate this therapy modality." (PMID 35372515, 2022). "How CXCL8 influences tumor metabolism and subsequently facilitate cancer proliferation needing further investigation." (PMID 35372515, 2022). "An increased level of anti-apoptotic proteins, mainly Bcl-2 and Bcl-xL, and a decreased level of pro-apoptotic proteins Bax and Bcl-xS determined the increased tumor cell survival mediated by CXCL8." (PMID 35269652, 2022). "The release of tumor recruitment–soluble factors, such as CXCL8, CXCL1, CXCL5, CXCL7, IL-6, and IL-1β, enhances immunosuppressive neutrophil chemotaxis through CXCR2 sensing, found to be highly expressed in NSCLC patients." (PMID 35874749, 2022).
tumor (continued). "The tumor-mediated overexpression and secretion of the chemokine IL-8 (CXCL8) have been utilized as leverage to maximize the tumoricidal effects of CAR-Ts in solid tumors by increasing the intratumoral trafficking of these cells." (PMID 35634281, 2022). "TAMs highly express IL-6, CXCL-8, and IL-10, which promote tumor cell growth, suppress the immune response of cytotoxic T cells and reduce the effects of chemotherapy." (PMID 36591450, 2022). "MSCs and NET can also form a positive pro-tumor feedback loop with osteosarcoma and glioma cells via CXCL8, respectively." (PMID 35372515, 2022). "The Kaplan-Meier test (STATISTICA 13.0 (StatSoft, USA) was used to assess the effect of the level of CXCL8 in the tumor on progression-free time." (PMID 36517518, 2022). "CXCL8 derived from tumor can act in a paracrine manner to change the composition of immune infiltration in TME, resulting the accumulation of pro-tumorigenic immune cells and tumor immune suppression." (PMID 35372515, 2022). "Phosphatidylinositol-3 kinase (PI3K)/Akt is one of the principal downstream signal of CXCL8, which plays vital roles in modulating tumor motility, angiogenesis, and survival." (PMID 35372515, 2022). "Compared to fibroblasts from normal tissues, the top upregulated genes in tumor-derived fibroblasts were CXCL8, CXCL2, CCL2, CXCL3 and CXCL1, and the top downregulated genes were IGFBP5, PTGDS, CCN5, CFD, and RAMP1." (PMID 36357663, 2022). "CXCL8 is highly expressed in a wide range of tumor types, and various studies have suggested that the CXCL8 serum level in tumor patients serves as an independent prognostic marker." (PMID 36091114, 2022). "CXCL8 is a multifunctional proinflammatory chemokine, which is significantly upregulated in tumor and tumor microenvironment as a key regulatory role." (PMID 35321506, 2022). "A recent investigations indicates that tumor cells can secret CXCL8 to impair the functions of NK cells via STAT3 signaling." (PMID 35372515, 2022). "This study discovered that the expression levels of CXCL9-14 in DLBCL were higher than those in normal tissues, while CXCL4, CXCL7 and CXCL8 were lower in tumor than in normal tissues." (PMID 35181719, 2022). "Some studies have shown that CXCL8 directly contributes to tumor microenvironment remodeling, cancer plasticity, and development of resistance to chemotherapy and immunotherapy." (PMID 35905218, 2022). "Serum CXCL-8 levels were significantly correlated with the M stage (p = 0.039) and tumor size (p = 0.034) in patients with CRC." (PMID 36567905, 2022). "In previous studies, CXCL8 (IL-8), as a major pro-inflammatory chemokine, mediates tumor immune escape through extracellular binding of two G-protein-coupled receptors (CXCR1 and CXCR2)." (PMID 36532065, 2022). "The mean score for stromal CXCL8 was 0.79 copies per μm2 (n = 386) and for CXCL8 within tumour cells was 0.58 copies per μm2 (n = 387)." (PMID 35879507, 2022). "To clarify the role of CXCL8 or LSECtin in tumor immune microenvironment and ICIs therapy, we carried out further analysis on immune cells infiltration and ICIs markers." (PMID 36358719, 2022). "The mean survival time for patients with tumours low for both stromal CXCL8 and CD68+ infiltration was 167 (95% CI: 150–184) months compared to 156 (95% CI: 141–170) months for one high and 122 (95% CI: 104–141) months for both low." (PMID 35879507, 2022). "On the contrary, delayed anti-PD1 treatment showed limited benefits associated with CXCR2+ myeloid cell recruitment in response to tumor secreted CXCL8." (PMID 35664746, 2022). "Pearson correlation analysis revealed a weakly positive correlation between CXCL8 expression counts from the stroma and tumour cell compartments (r = 0.224, p < 0.001)." (PMID 35879507, 2022). "Studies have shown that MMP9 and CXCL8 can be biomarkers to predict prognosis and indicate a more aggressive phenotype of tumor." (PMID 35321506, 2022).
tumor (continued). "The expression of CXCL8 in ESCC tumor tissues is positively correlated with tumor progression and poor survival." (PMID 36295640, 2022). "In terms of the mechanisms of tumour promotion, there is evidence that secretion of CXCL8 promotes many of the hallmarks of cancer." (PMID 35879507, 2022). "CXCR2 and its ligands were described as having an antimetastatic role in renal cell carcinoma where CXCL5 and CXCL8 produced by tumor cells can attract neutrophils with antitumor activity." (PMID 35158948, 2022). "The CXCL8 (IL-8) chemokine through its binding to CXCR1 or CXCR2 receptors supports tumor progression, partially promoting neutrophils and PMN-MDSCs recruitment." (PMID 35158779, 2022). "The high levels of CXCL8 and MIF are also suggestive of involvement of tumor-associated macrophages." (PMID 36230823, 2022). "The outcomes suggested that there is a notable correlation between CXCL8 and tumor purity, CD8+ T cells, macrophages, neutrophils, and DCs." (PMID 36532065, 2022). "In human cancer, the CXCR2 ligand CXCL8 (IL-8) is abundantly secreted by various tumor types and is sufficient to regulate neutrophil recruitment and NETosis." (PMID 35522219, 2022). "CXCL8 plays an essential regulatory role for cell motility, survival, angiogenesis, and proliferation in the tumor microenvironment and is also involved in regional anti-tumor inflammatory responses." (PMID 35922850, 2022). "The high frequency of tumour buds was associated with increased stromal CXCL8 expression (p = 0.010) and to a lesser extent tumour CXCL8 mRNA copies (p = 0.116)." (PMID 35879507, 2022). "Survminer cut‐off point analysis using the continuous variables determined the optimal cut‐off point for high and low expression to be 0.32 copies per μm2 for stromal CXCL8 and 0.65 copies per μm2 for tumour cell CXCL8." (PMID 35879507, 2022). "In line with it being a chemokine that promotes migratory processes, CXCL8 was found in the past to elevate tumor cell invasion, often through autocrine circuits." (PMID 35205789, 2022). "All tumor samples were divided into two groups based on the median expression of CXCL8 or CXCL5 and compared." (PMID 34025668, 2021). "This pro-resistance context attracts tumor-associated macrophages and stimulates the endothelial cell population through the release of CXCL8/IL8 and CCL5 by TNBrCa cells." (PMID 34201840, 2021). "Our investigations revealed that serum concentrations of CXCL-8, similar to those of the classical tumor marker, were significantly higher in patients with CRC in comparison to healthy controls—the results are consistent with those obtained by other authors." (PMID 34071492, 2021). "HCC-derived CXCL8 enhances tumor invasion and migration by promoting M2-type TAM accumulation and EMT." (PMID 35011369, 2021). "We also demonstrated statistically significant differences between CXCL-8 concentrations and tumor stages, and the presence of distant metastasis (M-factor)." (PMID 34071492, 2021). "MCP-1 (CCL2) and IL-8 (CXCL8) are chemokines known to allow tumor progression by promoting tumor angiogenesis." (PMID 33863290, 2021). "Chemokines, such as C–X–C motif chemokine ligand 8 (CXCL8) or C–C motif chemokine ligand 2 (CCL2) secreted by tumor cells also promote the accumulation of immunosuppressive cells at the tumor site." (PMID 34220833, 2021). "Notch 1 activation is required for the induction of CXCL8 in tumor–stroma interactions and consequently for prometastatic activities." (PMID 35011369, 2021). "Simultaneously, ESCC patients have higher levels of circulating CXCL8 compared to healthy controls, and the level correlates with tumor size and metastasis." (PMID 33390169, 2021). "In the TME, tumor cells recruit immature DCs from the peripheral blood by releasing multiple cytokines (e.g., VEGF, β-defensin, CXCL12, HGF, and CXCL8), which lack the ability to inhibit tumor angiogenesis." (PMID 34294146, 2021).
tumor (continued). "Treatment with a small-molecule antagonist of CXCR1/2, the receptor of CXCL8, was demonstrated to promote tumor progression in animal models established with CT26 cancer cells." (PMID 34025668, 2021). "IL8 (CXCL8) participates in most phases of tumor development from cell proliferation and angiogenesis to cancer metastasis." (PMID 34072741, 2021). "Numerous studies have shown that CXCL8 is expressed on endothelial cells, tumor-related macrophages and cancer cells, including CRC cells." (PMID 34025668, 2021). "CXCL8 is an important cytokine secreted by tumor cells that participates in initiating TME, maintaining CSCs function, and leading drug resistance." (PMID 34217295, 2021). "The CXCL8-CXCR1/2 axis has been shown to be tightly connected with the neutrophil or MDSC recruiting, and CXCL8 can directly or indirectly affect the function of almost all immune cell types, thereby influencing tumor development." (PMID 35011369, 2021). "Higher percentages of CD56+CD8+ T cells and mucosal-associated invariant T cells and lower percentages of CXCL8-producing myeloid cells were found both in PMBC and tumor samples after treatment." (PMID 35011369, 2021). "The chemokine receptor CXCR2 and its ligands CXCL1, CXCL2, CXCL3, CXCL5 and CXCL8 play critical roles in the chemoattraction of neutrophils towards tumor tissues." (PMID 34429454, 2021). "Emerging roles of the microbiome in tumorigenesis or tumor progression revealed the intricate interactions between inflammatory response, dysbiosis, metabolites, CXCL8, immune cells, and the TME." (PMID 35011369, 2021). "CXCL8 promotes tumor angiogenesis by maintaining the proliferation and activity of endothelial cells, and CXCR1 and CXCR2 are the basis of this function." (PMID 33767987, 2021). "The spleen is known as the site of TAN precursor localization, from which they physically relocate to tumor stroma, whereby CXCL8 (IL-8) is mainly responsible for the recruitment of TANs." (PMID 35003081, 2021). "As a marker of ESCC, NEDD9 maintained the stemness of ESCC cells and regulated CXCL8 through the ERK pathway to recruit MDSCs into the tumor, suggesting NEDD9 as a therapeutic target and novel prognostic marker for ESCC." (PMID 33710809, 2021). "Previous findings showing that tumour-derived MSCs secreted CXCL8 regulated by the NF-κB pathway were also confirmed in other tumours, and we extended these observations further by identifying the upstream regulator." (PMID 34650058, 2021). "The application of CXCL8 for the diagnosis of CRC is more practical than the use of the classical tumor marker CEA." (PMID 34439306, 2021). "Our results suggest that EOC cells can potentially secret CXCL2 and CXCL8 to TME that act autocrinally on tumor cells CXCR2, conferring the poor prognosis of the disease that is inferred by low patients’ OS." (PMID 34038868, 2021). "After 24 h of incubation, the number of migrated HUVECs was significantly elevated following culture in tumor supernatants and medium containing CXCL8 relative to that of HUVECs cultured only in medium." (PMID 34124076, 2021). "The diagnostic accuracy (ACC) of CXCL8 (77%) was higher than CXCR2 (70%) and classical tumor markers, CEA (48%) and CA19-9 (66%), but lower than for CRP (79%)." (PMID 34680333, 2021). "Using CT26 tumor tissues, we analyzed the DC activation genes by qRT-PCR, and the results supported the relationship between CXCL8 and DCs activation marker in TCGA cohort." (PMID 34025668, 2021). "Mast cells also produce CXCL8/IL-8 which can induce epithelial-to-mesenchymal transition (EMT) in which tumor cells acquire metastatic features and resistance to chemotherapy." (PMID 34712668, 2021). "The CXCL8 knockdown using an antisense vector led to the increase in cell death and the decrease in tumor growth in mouse models carrying xenografts." (PMID 34885171, 2021).